ACOD1 (aconitate decarboxylase 1)
Diseases named in the same sentence as ACOD1 in open-access papers (continued):
Sharing a sentence is not in itself a finding about the gene and the disease.
breast tumors (1 paper, 2024). "An Acod1+ TAN subset, which defends against ferroptosis and promotes cancer metastasis via an Acod1-dependent immunometabolism switch, has also been identified in human breast tumors." (PMID 39614322, 2024).
epilepsy (1 paper, 2025). A brain disorder characterized by episodes of abnormally increased neuronal discharge resulting in transient episodes of sensory or motor neurological dysfunction, or psychic dysfunction. "Therefore, this work provides a new perspective that CA can be used as a novel therapeutic agent for epilepsy and neuroinflammation-related disorders, with ACOD1 as a potential target for CA’s anti-neuroinflammatory effects." (PMID 39901156, 2025).
Granuloma (1 paper, 2025). A compact, organized collection of mature mononuclear phagocytes, which may be but is not necessarily accompanied by accessory features such as necrosis. "Our spatial transcriptomics data provide gene expression patterns at single-cell resolution within cryptococcal granulomas and reveal highly heterogenous myeloid cells in the granuloma center, some of which appear highly interferon-responsive based on expression of Il1rn, Nos2 and Acod1." (PMID 40568097, 2025).
Hypercholesterolemia (1 paper, 2023). An increased concentration of cholesterol in the blood. "Taken together, our results show that Acod1 in macrophages protects mice from atherogenesis during hypercholesterolemia." (PMID 38085578, 2023). "Fat mass also increased with hypercholesterolemia, and although Acod1–/– mice initially had a higher fat mass than WT mice, this difference was eliminated after week 6 of hypercholesterolemia." (PMID 38085578, 2023). "WT and Acod1–/– mice displayed comparable plasma cholesterol levels throughout the hypercholesterolemia regimen." (PMID 38085578, 2023). "Indeed, we observed larger atherosclerotic lesions in both the aortic root and brachiocephalic artery (BCA) of Acod1–/– mice compared with WT after 10 weeks of hypercholesterolemia." (PMID 38085578, 2023). "WT and Acod1–/– mice had similar body weights that increased due to hypercholesterolemia." (PMID 38085578, 2023). "WT and Acod1–/– mice had similar liver weights, gonadal white adipose tissue (GWAT) weights, liver lipid droplet accumulation, and GWAT adipocyte sizes after 10 weeks of hypercholesterolemia." (PMID 38085578, 2023). "To determine whether Acod1 plays a role in atherogenesis, we examined Acod1–/– C57BL/6N mice before and during hypercholesterolemia." (PMID 38085578, 2023). "Importantly, hypercholesterolemia resulted in elevated levels of itaconate in the aortas of WT mice but not Acod1–/– mice (P < 0.0001)." (PMID 38085578, 2023).
influenza (1 paper, 2022). An acute viral infection of the respiratory tract, occurring in isolated cases, in epidemics, or in pandemics; it is caused by serologically different strains of viruses (influenzaviruses) designated A, B, and C, has a 3-day incubation period, and usually lasts for 3 to 10 days. "Further research is necessary into possible sex-specific effects of the Acod1 gene in influenza infection." (PMID 35025971, 2022). "Thus, induction of ACOD1 expression (and thereby itaconate synthesis) likely is a common feature in human influenza." (PMID 35025971, 2022). "Of note, we found upregulation of ACOD1 mRNA by IAV infection in myeloid cells and in blood from patients with moderate and severe influenza infection." (PMID 35025971, 2022). "The induction of ACOD1 mRNA expression in peripheral blood in IAV infection was also corroborated by reanalysis of a published dataset from whole blood from patients with moderate and severe influenza." (PMID 35025971, 2022).
keloid (1 paper, 2024). An irregularly shaped, elevated mark on the skin caused by deposits of excessive amounts of collagen during wound healing. "It shows that keloid tissues display ACOD1 expression deep under the epidermis, while normal adjacent tissues display ACOD1 presence mostly close to the surface." (PMID 39081787, 2024). "We noticed that ACOD1 expression is lower in the marginal part of keloids than in the central part of the keloid tissue at the whole protein level." (PMID 39081787, 2024). "Among the genes induced in keloids are Tlr1, Tlr2, Tlr6, and Acod1, commonly up-regulated by bacteria." (PMID 39081787, 2024).
leishmaniasis (1 paper, 2025). Infectious disease that is transmitted through the bite of hematophagous female phlebotomine sand flies. "Itaconate, produced by the Acod1 gene, is recognized for its anti-inflammatory effects, but its function in leishmaniasis is not well understood." (PMID 40142422, 2025). "The differential kinetics of Acod1 and Il1b expression in L. major-infected BMDMs may support the hypothesis that itaconate contributes to the progression of leishmaniasis by inhibiting M1 macrophage polarization and potentially driving an M2-mediated response." (PMID 40142422, 2025).
lupus (1 paper, 2024). "Overall, results indicate that ACOD1 modulates pathogenic autoAb synthesis, kidney immune complex deposition and renal injury, and systemic inflammatory cytokine production in lupus-prone mice." (PMID 38605883, 2024). "To analyze the effect of ACOD1 absence in other myeloid cells, we tested the ability of BM-derived neutrophils to form NETs, a feature that is dysregulated in murine and human lupus in association with aberrant mROS synthesis." (PMID 38605883, 2024). "We have now expanded our investigations on the putative roles of the endogenous ACOD1/ itaconate pathway in mouse and human lupus." (PMID 38605883, 2024). "Here, we explore the role of the endogenous ACOD1/itaconate pathway in the development of murine lupus as well as their relevance in premature cardiovascular damage in SLE." (PMID 38605883, 2024). "We have investigated the role of ACOD1 (the enzyme responsible for itaconate production) in the development of systemic autoimmunity in an induced murine lupus model." (PMID 38605883, 2024). "In the IMQ-induced mouse model of lupus, ACOD1 knockout (Acod1−/−) displayed disruptions of the splenic architecture, increased serum anti-dsDNA and proinflammatory cytokine levels, enhanced kidney immune complex deposition and proteinuria, when compared to the IMQ-treated WT mice." (PMID 38605883, 2024). "However, our previous observations that exogenous analogs of itaconate can improve NZB/W F1, another lupus mouse model, and that levels of ACOD1 decrease in these genetically prone mouse model as nephritis progresses, suggests that these observations are not model-dependent." (PMID 38605883, 2024). "Givne that, to our knowledge, there were no previous reports on whether TLR7 engagement ( a lupus-relevant pathway) would induce ACOD1, we performed an in vitro time-course on WT and Acod1−/− bone marrow-derived macrophages (BMDM) following incubation with IMQ." (PMID 38605883, 2024).
overnutrition (1 paper, 2024). An imbalanced nutritional status resulting from excessive intake of nutrients. "For this aim, we measured responses to overnutrition in both wild type and Acod1-/- (recipient) mice after prolonged oral transfer of feces from their reciprocal genotype (donor) counterparts, all fed with HFD." (PMID 38302438, 2024).
promyelocytic leukemia (1 paper, 2025). "Subsequently, in vitro experiments using mouse PBNs and dHL60 cells (a human promyelocytic leukemia cell line with neutrophil‐like differentiation) were conducted to assess the effect of Acod1 on inflammatory factor release and NETs formation." (PMID 40586264, 2025).
infection (99 papers, 2012 to 2025). The state of being infected such as from the introduction of a foreign agent such as serum, vaccine, antigenic substance or organism. "Strikingly, only a discrete set of immune genes (including genes encoding the aconitate decarboxylase Acod1 and the G-protein coupled receptor Gpr84) remain differentially expressed at 24 h post-infection (hpi), suggesting an important role for these markers in host survival." (PMID 38131137, 2024). "We find that loss of ACOD1 and itaconate synthesis led to increased inflammation during infection and that exogenous itaconate, DI, and 4OI substantially reduced inflammation, most notably IFN responses, whereby some pro-inflammatory effects were seen with unmodified itaconate." (PMID 35025971, 2022). "Thus, although we interpret the unimpeded growth of NMII during the first week of infection as the major driver of inflammation and clinical disease in Acod1−/− mice, the loss of immunoregulatory functions of ACOD1 may contribute." (PMID 36479617, 2023). "It is therefore tempting to speculate that one beneficial role of an active ACOD1/itaconate axis is to reduce the risk of death or organ damage from infection-associated inflammation and that loss-of-function genotypes have been selected against during times of high infectious disease burdens." (PMID 35025971, 2022). "Aconitate decarboxylase 1 (ACOD1, also known as immune-responsive gene 1, IRG1) is a critical regulator of immunometabolism and inflammation, particularly in the context of infection and injury." (PMID 40703506, 2025). "Active and VBNC infection of M0-BMDM induced a strong expression of these glycolytic genes at 24 h post-infection, and infection with HK + 1 induced the expression of Hk2, Pfkfb3, and Acod1." (PMID 39714095, 2025). "The upregulation of ACOD1 occurs in activated immune cells in response to pathogen infection, PAMPs, inflammatory cytokines, hormones and damage-associated molecular patterns." (PMID 41398915, 2025). "Mt1, Acod1, and Gm15564 were also upregulated with infection in HIF-α competent macrophages, indicating these transcriptional changes are independent of HIF-α signaling." (PMID 40191198, 2025). "S. anginosus infection significantly upregulated ACOD1 protein expression in macrophages compared to untreated macrophages in 6 h post-infection." (PMID 38289109, 2024). "Similar to our results, previous transcriptomic research in chickens has also shown increases in expression of TLR1B, CXCL12 and ACOD1 after infection with MG." (PMID 38370402, 2024). "Infection from Salmonella Typhimurium or Mycobacterium avium is also restricted by the induction of ACOD1 expression or itaconate production." (PMID 39351225, 2024). "ACOD1 is a multifunctional regulator of infection and inflammation responsible for itaconate metabolism and is found predominately in the mitochondria." (PMID 39351225, 2024). "As ITA is an immunomodulatory agent, we measured the pro-inflammatory cytokines TNF, IL-6, and IL-1β, and the anti-inflammatory cytokine IL-10 in cell culture supernatants 24 hours after NMII infection of Acod1+/- and Acod1-/- BMM." (PMID 39156902, 2024). "The strong phenotype of Acod1-/- mice in experimental infection with M. tuberculosis, with high bacterial burden and early death, was coupled to excessive accumulation of neutrophils in the lungs and the development of neutrophil-mediated immunopathology." (PMID 38487538, 2024). "Countering the effects of HIF1A and succinate, aconitate decarboxylase 1 (ACOD1) acts as a regulator of the inflammatory response to infection and other inflammatory stimuli." (PMID 39415736, 2024). "More recently, also neutrophils have been identified to upregulate ACOD1 mRNA expression to high levels in infection and tumor models." (PMID 38487538, 2024). "Further, TFEB translocation driven by LPS or infection with Salmonella typhimurium was abrogated in Acod1-/- macrophages, but recovered by 4-OI." (PMID 38487538, 2024).
infection (continued). "To assess the role of Acod1 in Lyme carditis, which peaks at two weeks post infection in wild type mice, we subcutaneously infected Acod1-/- and C57BL/6NJ WT mice and terminated at two weeks." (PMID 38157387, 2023). "Immunohistochemistry for C. burnetii in the lungs confirmed a strongly increased bacterial load in Acod1−/− mice on day 7 after i.t. infection." (PMID 36479617, 2023). "Seven days after infection, the bacterial burden in the lungs of Acod1−/− mice was more than 10‐fold higher than in wild‐type or Acod1+/− animals." (PMID 36479617, 2023). "Previous studies have shown that Acod1 and Il6 play an important role as immune regulators in maintaining homeostatic balance in the host and that the accumulation resulting from the infection response confers a powerful proinflammatory response to the host." (PMID 37643174, 2023). "It will therefore be important to investigate the role of the ACOD1‐itaconate pathway in infection with virulent C. burnetii NMI in future work." (PMID 36479617, 2023). "Consistent with reduced IFNγ expression, the mRNA induction of Nos2, Gbp1, Gbp2, Gbp4, Gbp5, Ido1 and Acod1 was severely impaired in the spleens of Myd88−/− mice after intraperitoneal infection." (PMID 36479617, 2023). "We show that the immunosuppressive effects of Acod1 were maintained, over time, in a mouse infection model." (PMID 38157387, 2023). "We examined one of the most highly expressed negative regulators of immune pathways during primary stimulation, Aconitate decarboxylase 1 (Acod1), and tested its effects during in vivo infection with Bb." (PMID 38157387, 2023). "We specifically investigate Acod1 as relevant in memory induction and demonstrate an in vivo role during long-term infection with Bb." (PMID 38157387, 2023). "Infection of mice with C. burnetii induced expression of several anti‐microbial candidate genes, including Acod1." (PMID 36479617, 2023). "Single-cell RNA sequencing identified monocytes as the main target of infection and the exclusive source of ACOD1 mRNA in peripheral blood." (PMID 35025971, 2022). "To this end, we activated dTHP1 cells with LPS/IFN-γ, which results in maximal activation and much higher ACOD1 expression than infection with viruses such as IAV." (PMID 35655026, 2022). "Infection induced expression of ACOD1, the enzyme catalyzing itaconate synthesis, in monocytes and macrophages, which correlated with viral replication and was abrogated by DI and 4OI treatment." (PMID 35025971, 2022). "Infection of dTHP-1 cells with three IAV (H1N1) strains of differential replication efficiency showed the strongest ACOD1 and TNFAIP3 induction by the two strains with the highest and the weakest by the strain with the lowest replication efficiency." (PMID 35025971, 2022). "The recent medical studies indicated that ACOD1 is markedly up-regulated by pathogen infection and serves as a key regulator of inflammation and infection." (PMID 35163263, 2022). "Itaconate also inhibits the function of phagocytes to eliminate pathogens, indicating a dual role of the ACOD1-itaconate axis in infection." (PMID 35769880, 2022). "We have shown previously that Acod1 transcription in the first 48 h of infection is higher in IAV-infected lung from DBA/2J than from C57BL/6J mice." (PMID 35025971, 2022). "A reanalysis of our RNAseq data from a longer time course showed that this difference persisted at least through day 3 post infection (p.i.)and that Acod1 expression nearly normalized by day 14 in the surviving strain." (PMID 35025971, 2022). "We found that the infection significantly upregulated the expression of Acod1 and its downstream genes (Atf3, Stat3, Nfe2l2 and Nrf2, etc.)." (PMID 36618398, 2022). "Of note, our lncRNA microarray analysis showed that larval E. granulosus infection can upregulate the expression of SUCNR1 and ACOD1 in adipose tissues of mice, which is paralleled with the M2 macrophage polarization post infection." (PMID 35281054, 2022).
infection (continued). "We observed that Acod1-/- mice infected with B. melitensis only displayed significantly enhanced CFU at 9 days post-infection in the lungs, compared to wt mice." (PMID 34525130, 2021). "Using RNA sequencing, we identified the aconitate decarboxylase 1 gene (Acod1; also known as Immune responsive gene 1), as one of the genes most upregulated in murine AMs in response to B. melitensis infection at 24 hours post-infection." (PMID 34525130, 2021). "In contrast, CFU counts were significantly enhanced at 2-, 5- and 9-days post-infection in Acod1-/- mice infected with B. abortus." (PMID 34525130, 2021). "ACOD1 serves a multifaceted role in the innate immune response to pathogen infection (bacteria and viruses) and in cytokine signaling (TNF and interferons), and is associated with both Toll-like receptor and NF-kB signaling pathways." (PMID 34399690, 2021). "IRG1 was shown to be an essential component of the immune response to M. tuberculosis, as Acod1−/− mice succumbed more rapidly than wild-type mice to infection." (PMID 31719183, 2019). "Our results showed that Acod1 and Il1b were expressed at different timepoints, with IL-1β being expressed in L. major-infected BMDMs at early timepoints, while Acod1 expression occurred later in the course of the infection." (PMID 40142422, 2025). "The activation of the ACOD1 pathway may limit pathogen infection, but abnormal ACOD1 expression can lead to tumor progression, neurodegenerative disease and immune paralysis." (PMID 41398915, 2025). "Four weeks after infection, pulmonary ACOD1 expression in HFD mice was significantly elevated." (PMID 39921443, 2025). "At 3 h and 6 h post-infection, Il1b expression lost statistical significance, whereas Acod1 showed significant upregulation in L. major-infected macrophages in comparison to non-infected BMDMs at both time points (p-value = 0.0077 and p-value = 0.0121, respectively)." (PMID 40142422, 2025). "Four weeks post‐infection, ACOD1 mRNA and protein levels were significantly reduced in the lungs." (PMID 39921443, 2025). "However, during immune responses in vivo, especially in certain infections, ACOD1 expression and itaconate production will occur concomitantly with IL-4 secretion (e.g. by ILC2 and Th2 cells)." (PMID 38487538, 2024). "BMM deficient in ACOD1, the inducible mitochondrial enzyme responsible for ITA production, cannot restrict NMII replication and contain a >10-fold higher bacterial burden compared to Acod1+/- BMM at 96 hours post infection." (PMID 39156902, 2024). "The enhanced production of IFNγ and of several of its anti‐microbial target genes between day 7 and 11 after infection may explain the ability of Acod1−/− mice to resolve NMII infections despite an initial increase in bacterial replication." (PMID 36479617, 2023). "Interestingly, blockage of the Krebs cycle and disorder of the ACOD1-itaconate axis were identified to be the metabolic phenotypes in the prefrontal cortex post infection." (PMID 37256871, 2023). "In addition, the metabolic phenotype of the prefrontal cortex post infection was characterized by the enhancement of glycolysis and fatty acid oxidation, the blockage of the Krebs cycle, and the disorder of aconitate decarboxylase 1 (ACOD1)-itaconate axis." (PMID 37256871, 2023). "ACOD1 produces itaconate in response to pathogen infection and inflammation." (PMID 37723178, 2023). "The expression of Irg1 encoding ACOD1 shows basal level in nonactivated macrophages, though the gene level is induced upon infection with live pathogens or LPS stimulation." (PMID 37261340, 2023). "Observing the activated ACOD1-itaconate axis post infection, we were interested in whether the administration of Dimethyl itaconate (DI), a cell-permeable itaconate derivative, could modulate the neuroinflammation induced by T. gondii." (PMID 37256871, 2023). "Infection of primary murine and human macrophages in vitro rapidly triggered expression of Acod1." (PMID 36479617, 2023).